FPR1 (formyl peptide receptor 1)
Diseases named in the same sentence as FPR1 in open-access papers (continued):
Sharing a sentence is not in itself a finding about the gene and the disease.
tumor (continued). "All these data demonstrate that FPR1 may play an important role in cancer development and invasion, and may represent a therapy option for the treatment of these neoplasms." (PMID 28724995, 2017). "Furthermore, the functions of FPR1 in tumor invasion and tissue repair were investigated using the CRC cell lines SW480 and HT29." (PMID 28724995, 2017). "The induction of FPR1 may trigger a wide variety of effects attributed to tumor growth such as increased vascular permeability and angiogenesis, chemotaxis, cell adhesion, as well as cell survival and proliferation." (PMID 27432059, 2016). "Similar effects of FPR1 stimulation have recently been described in both normal and tumor cells." (PMID 27432059, 2016). "Furthermore, the inhibition of FPR1 activity in NB cells resulted in a decreased tumor growth in a xenograft model while overexpression resulted in an increased tumor load, suggesting a role for FPR1 in the development of an aggressive phenotype." (PMID 27432059, 2016). "This indicates that FPR1 expression is present on tumor cells as well as on macrophages." (PMID 25894595, 2015). "This discrepancy could be the result of heterogeneous FPR1 expression within the tumor or of FPR1 being mostly present on immune cells." (PMID 25894595, 2015). "In contrast to wild-type (WT), Fpr1-/-, and Fpr2-/- mice, neutrophils were almost completely absent in 4T1 tumors from Cxcr2-/- mice, indicating a dominant role for CXCR2 in the recruitment of tumor-associated neutrophils, leading us to use Cxcr2-/- mice for further studies." (PMID 41977328, 2026). "Furthermore, FPR1 deletion in CRC cells strongly impaired tumor-specific immune response, by reducing the ability of Dendritic cells (DCs) to migrate toward dying CRC cells, thus favoring colonic reactive hyperplasia and inflammation-induced colon tumorigenesis." (PMID 41425092, 2025). "Thus, we may conclude that CTHRC1 may induce tumor associated macrophage infiltration though GRN/TNFRSF1A and AnxA1/FPR1 pathways." (PMID 35928443, 2022). "However, other results pointed to FPR1 as a tumor suppressor in this same cancer type." (PMID 34571894, 2021). "Indeed, we found that the level of FPR1-expression in U87-MG cell line in 2D culture increased under hypoxic and serum deprivation stress conditions, which correlate to those experienced within the tumour’s core." (PMID 33057069, 2020). "In addition, FPR1 is shown to contribute to the expansion of different tumour types." (PMID 33057069, 2020). "Thus, we examined whether FPR1 was expressed in the colorectal epithelium and tumor-infiltrating neutrophils and macrophages." (PMID 28724995, 2017). "Our data demonstrate that FPR1 may play an important role in tumor cell invasion in CRC patients." (PMID 28724995, 2017). "As the expression of FPR1 in the infiltrating leukocytes are well expected and may be an important part of the tumor microenvironment, the increased expression of FPR1 in CRC epithelial cells is of interest to us and suggests a correlation with the invasiveness of CRC." (PMID 28724995, 2017). "We assume that FPR1 expressed by NB cells may be activated by formylated peptides released from the mitochondria or by other compartments of necrotic tumor cells, locally acting as trophic factors which promote FPR1-driven inflammatory signaling pathways, amplified growth and invasiveness." (PMID 27432059, 2016). "Only advanced-stage EOCs appeared to be characterized by a scenario that involves genes such as FPR1, KLF2 and THBD, to date associated with thrombosis and cardiovascular disease, thus suggesting that this pathway contributes to the growth and/or the spread of this type of tumor." (PMID 23889749, 2013). "Mechanistically, tumor-derived CypA specifically from PCa cells bound to ANXA6 and activated the downstream FPR1 signaling pathway, leading to increased mitochondrial oxidative phosphorylation and NK cell activation." (PMID 41591831, 2026).
tumor (continued). "For example, neutrophils and NK cells showed significant interactions with tumour cells through pathways such as MIF‐(CD74 + CXCR4) and ANNEXIN‐(FPR1 + FPR2), which are known to modulate immune responses and tumour progression." (PMID 40099956, 2025). "On the contrary, our study unravels a direct cellular interaction between tumor cells and DCs (ANXA1:FPR1/3), which induces apoptosis of DC." (PMID 40484878, 2025). "CXCL10, P2RX7, TLR3, and TLR4 were significantly upregulated in IS2 tumours in the TCGA cohort, whereas ANXA1, CXCL10, FPR1, IFNAR2, P2RX7, and TLR4 showed significantly higher expression levels in IS4 tumours in the GEO cohort." (PMID 36851274, 2023). "Gene Set Enrichment Analysis revealed that A2M promoted tumor development through enhancing immune cell related signal pathways, while CD163 and FPR1 inhibited tumor development through activated carcinogenic signal pathways." (PMID 38115318, 2023). "Regarding the evidence that IL-6 signaling elicits the AnxA1/FPR1 axis leading in TNBC cells, we tested the in vivo effect of this receptor inhibition on tumor growth and fibroblast migration." (PMID 35626741, 2022). "A key modulator of SPM production was the Formyl Peptide Receptor 1 (FPR1), which functions in the GI tract as a tumor suppressor." (PMID 35884394, 2022). "Although DC recruitment into the tumor bed is mainly mediated by additional chemokines and ATP, ANXA1 guides DCs towards dying cancer cells by interacting with formyl peptide receptor 1 (FPR1)." (PMID 36010596, 2022). "ANXA1 binds formyl peptide receptor 1 (FPR1) thus facilitating DC homing to dying cells in the tumor bed, and CALR stimulates tumor antigen engulfment by DCs." (PMID 33809187, 2021). "In human breast cancer cells, FPR1 and FPR2 interact with ANXA1 to enhance tumor cell proliferation." (PMID 33804219, 2021). "FPRs, especially FPR1 and FPR2, have been shown to play a role in the development of several pathological conditions, such as neoplasms and inflammatory diseases." (PMID 34220836, 2021). "Nevertheless, although diabetes has been shown to be associated with more rapid progression of GBM and higher patient mortality, the connection with the levels of FPR1 and EGFR in tumor remains to be established in the clinic samples." (PMID 32038501, 2020). "Next, we examined the correlation between Fpr1 SNPs with clinicopathological characteristics which included sex, age, AJCC stage and location of tumor, tumor size, differentiation, lymphatic invasion, distant metastasis, and pathological type." (PMID 32284754, 2020). "FPR1 and EGFR by their respective agonists to mediate tumor cell migration, growth and formation of cell colonies." (PMID 32038501, 2020). "Although no statistical evaluation was applicable for the lack of representativeness of LGSC, OCCC and mEOC cases, we observed that FPR1 is mainly expressed in HGSC tumors, and that 80% positive tumor cells observed in 20 out of 28 HGSC tissues." (PMID 31703596, 2019). "FPR1 expression levels were evaluated by assessing either the percentages of positive tumor cells/TAM punch, either staining intensity of tumor cells, graded as faint (score 0), moderate (score 1), or intense (score 2)." (PMID 31703596, 2019). "Significant upregulation of FPR1 protein level was found in CRC tissue compared with distant normal tissues and adjacent non-tumor tissues, which was consistent with its mRNA expression profile." (PMID 28724995, 2017). "Additionally supernatant from necrotic tumor cells may activate FPR1 on U87 cells." (PMID 25894595, 2015). "Among the most downregulated proteins, we found several confirmed or candidate tumour suppressor genes (eg, ID1, FAS, FPR1, IL10, PCGF2, VDR)." (PMID 25594007, 2014). "FPR1 selectively expressed by GBM cells when activated by exogenous and tumor derived agonists promotes tumor cells to produce proangiogenic factors VEGF and the angiogenic chemokine CXCL8." (PMID 25110692, 2014).
tumor (continued). "On the other hand, we found FAS, FPR1, ID1, IL10, PCGF2, VDR among downregulated proteins: all are involved in tumor immune-escape through induction of apoptosis and anti-inflammatory activities." (PMID 25594007, 2014). "Several of the GPCRs were formerly shown to be involved in tumour biology, such as AT1R, EDG2, DARC, and FPR1." (PMID 20386750, 2010). "Additionally, pro-tumor TANs were also recruited to the tumor area and interacted with Epi_10_CYSTM1, as well as Epi_07_CAPS and Epi_12_RRAD cells, via the ANNEXIN-to-FPR1/FPR2 signaling pathway." (PMID 40066698, 2025). "Additionally, research by Wu’s team indicated that CXCL6, produced by highly invasive tumor cells, stimulates the release of SAA from damaged hepatocytes, encouraging macrophage infiltration and polarization via FPR1 and TLR2 receptors." (PMID 39457484, 2024). "FPR1 was not required for DCs to mobilize into tumors, but it was necessary for DCs to approach dying tumor cells, take up TAAs, and cross-present to T cells." (PMID 34638242, 2021). "In support of this model, anticancer immunity after chemotherapy with anthracyclines was compromised in mice with tumours lacking AnxA1, or when the dendritic host cells lacked FPR1." (PMID 33810523, 2021). "In spite of the accumulating evidence supporting a role for FPR1 in cancer, as yet no small molecule specifically targeting FPR1 has been tested for in vivo efficacy in a tumour model." (PMID 33057069, 2020). "In CRC tissues, both colorectal epithelial cells (MPO negative) and tumor infiltrating myeloid cells (MPO positive) expressed FPR1." (PMID 28724995, 2017). "Furthermore, Hep1 cells localized in the invasive zone could secrete SAAs to regulate Formyl Peptide Receptor 1+ (FPR1+) macrophage recruitment and induce M2 polarization through SAAs-TLR2 axis, resulting in local immunosuppression and tumor progression." (PMID 37337030, 2023). "Although we have not yet investigated the drivers for the elevation of FPR1 expression in the periphery of the tumour core, we can speculate that may be partly due to hypoxia." (PMID 33057069, 2020). "Since the gMDSCs derived from metastatic 4T1 tumour-bearing animals were able to suppress the EMT-related genes and also induce distinct set of genes; S100A9, MMP8, S100A8, WFDC21, LYZ2, FPR1, CCL3, TGFb2, we reasoned whether these genes could be specific for metastatic/aggressive behaviour." (PMID 28382931, 2017). "FPR-2 rather than FPR-1, has been involved in tumor progression and metastases of several tumors." (PMID 26312765, 2015). "Besides fMLP, ligands for FPR1 also include non-microbial endogenous host-derived peptides such as mitochondrial formylated peptides fMMYALF, fMLKLIV and fMFADRW, Annexin A1 and Cathepsin G, that may be released by necrotic cells within the tumor microenvironment." (PMID 27432059, 2016).
infection (78 papers, 2008 to 2026). The state of being infected such as from the introduction of a foreign agent such as serum, vaccine, antigenic substance or organism. "To further examine the phenotype of CD16+ CD49d-/+PMNs, we have also analyzed relative expression of FPR1 that is implicated in pathogen recognition during infection." (PMID 37849757, 2023). "In adults however, because the CNS is more frequently associated with sterile inflammation than infection, the importance of FPR1 in protection against CNS-associated infection remains to be clarified." (PMID 36556373, 2022). "The depletion of FPR1 impairs neutrophil phagocytosis and killing of E. coli in vitro, and reduces neutrophil recruitment in vivo, a response associated with increased infection-induced mortality in mice." (PMID 36556373, 2022). "Among them, the main role of Fprs in pathogenic infection is Fpr1/Fpr2 mediated neutrophil recruitment in bacterial infection, that is, in L. monocytogenes infection, Fpr1/2 directly chemoattract neutrophils through the receptor itself before CXCL1/2 is produced." (PMID 34899755, 2021). "During cellular stress or mitochondrial damage provoked by trauma, inflammation, and infections, N-formyl peptides are released, and they have been implicated in the induction of inflammatory processes through the activation of neutrophils via the FPR1 and FPR2 receptors." (PMID 40733247, 2025). "During infections, FPR1 is also a crucial modulator of phagocyte degranulation and superoxide generation, by requiring Gi coupling." (PMID 40103822, 2025). "Infection led to a decrease in PECAM-1 signal in FPR1-KO mice, but Ac2-26 treatment significantly increased PECAM-1 immunofluorescence in infected FPR1-KO mice (p < 0.01)." (PMID 39768195, 2024). "In mice, formylated peptide receptors Fpr1 and Fpr2 detect formylated peptides produced by Lm and are required for neutrophil chemotaxis to the site of infection and ultimately Lm clearance." (PMID 37706879, 2023). "CAP proteins have been reported as novel virulence factors in pathogenic fungi during infection of the mammalian hosts, such as RBT4 in C. albicans and Fpr1 in F. oxysporum." (PMID 37504723, 2023). "Despite the discrepancy in receptor numbers across the two species, several receptors share similar functionality, including FPR1/Fpr1, both of which are known to respond to host infection and regulate chemotaxis." (PMID 36556373, 2022). "Within the periphery, FPR1 has a central role in responding to infections through binding to bacterial and mitochondrial derived formyl peptides." (PMID 36556373, 2022). "The infection with Streptococcus pneumoniae resulted in an increased GFAP+ cell density in Fpr1−/− and Fpr2−/− mice." (PMID 33121515, 2020). "For example, the high-affinity formyl peptide receptor, FPR1, plays a critical role in the initial recruitment of neutrophils to sites of inflammation and/or infection." (PMID 32076421, 2020). "FPR1 has a high affinity to formyl peptides produced by bacteria or released from damaged mitochondria during infection or tissue injury." (PMID 28751674, 2017). "In the present study we found upregulation of genes that encode the fMLP receptors (FPR1 and FPR2) in rabbit lungs as early as 3 hours after infection with HN878." (PMID 23958185, 2013). "Physiologically, this appears logical since FPR1 is one of the first receptors that is alerted to the presence of microorganisms, and directs the PMNs to the site of infection through chemotaxis." (PMID 22174875, 2011). "Notably, as the infection progressed to 35 dpi, Fpr1-inhibited mice displayed a significant increase in dead/dying neutrophils harboring Mtb, which corresponded with an elevated overall bacterial load in the lung." (PMID 38853986, 2024). "In contrast, some paired ligands and receptors, such as ANXA1_FPR1, C5AR1_RPS19, CCL5_CCR1, and PTPRC_MRC1, were significantly activated after infection, which may mediate the communication among T cells and myeloid cells." (PMID 37087411, 2023).
infection (continued). "Human FPR1 is activated after infection and sterile stimulation, leading to immune cell responses." (PMID 37803031, 2023). "Interestingly, our results demonstrated that interaction scores of some paired ligands and receptors (e.g., ANXA1_FPR1, CD74_APP, CD74_COPA, CXCL1_CXCR1, CXCL2_CXCR2, and HLA-F_LILRB2) were significantly increased after infection." (PMID 37087411, 2023). "Therefore, mitigating the “desensitizing” activity of FPR1 (Fpr1) has shown profound effect on protecting the host from systemic sterile inflammation and secondary infection following tissue injury or primary infection." (PMID 32038501, 2020). "Blockade of FPR1 by using receptor inhibitors (such as cyclosporin H) or gene deletion (Fpr1 KO) preserved normal neutrophil bacterial phagocytosis or superoxide production in response to trauma or infection." (PMID 32038501, 2020). "Using this in vitro infection, neutrophils from mice deficient in TLR2, NOD2 or FPR1 produced significantly less IL-1β protein (40, 43 and 37 percent decrease, respectively) in response to S. aureus, suggesting that activation of TLR2, NOD2 and FPR1 promoted neutrophil production of IL-1β." (PMID 23209417, 2012). "To test whether the FPR1-expressing dual-labeled cells would exhibit an enhanced response to bifunctional compounds, we inoculated control or pre-treated conidia into the circulation FPR1/mCherry-expressing larvae at 3 dpf, and scored phagocytosis at 2 h post-infection in the caudal venous plexus." (PMID 31024528, 2019). "N-formyl-Met-Leu-Phe (fMLF) is a model PAMP/DAMP driving human PMN to sites of injury/infection utilizing the GPCR, FPR1." (PMID 29785402, 2018). "Formyl Peptide Receptor 1 (FPR1) is a member of the human G protein-coupled receptor (GPCR) family in humans and plays a key role in mediating the chemotaxis of immune cells, particularly neutrophils and macrophages, to sites of infection and inflammation." (PMID 40861493, 2025). "During the initial stages of infection, there were no discernible differences in bacterial burdens between the Fpr1-inhibited and control groups." (PMID 38853986, 2024). "However, as the infection progressed, the absence of Fpr1 significantly compromised bacterial control, particularly within dead/dying neutrophils." (PMID 38853986, 2024). "Fpr1 expression is highly stimulated upon infection with R179NT M. tb, which is not observed in response to infection with R179T M. tb." (PMID 27055235, 2016).